MMP12 (matrix metallopeptidase 12)
Diseases named in the same sentence as MMP12 in open-access papers (continued):
Sharing a sentence is not in itself a finding about the gene and the disease.
emphysema (continued). "The increase in MMP-12 expression after a single exposure CB NPs could have important pathophysiological consequences because this protease plays a critical role in emphysema and COPD." (PMID 22849372, 2012). "It has been shown that an MMP-9/MMP-12 inhibitor can substantially ameliorate morphological emphysema in guinea pigs, suggesting that MMPs may be important mediators of the anatomical changes behind COPD." (PMID 19014449, 2008). "Indeed, mice lacking integrin αvβ6 (integrin αvβ6 null mice) fail to activate TGF-β and develop an age-related emphysema, which is MMP-12-dependent." (PMID 16504062, 2006). "Although the role of MMP-12 in animal models of emphysema is well documented, its involvement in pulmonary fibrosis remains unclear." (PMID 16504062, 2006). "Inflammatory cells might contribute to the development of pulmonary emphysema, since they have the capacity to secrete many elastolytic enzymes, such as neutrophil elastase (by neutrophils) and MMP-12 (by macrophages and dendritic cells)." (PMID 16359546, 2005). "This indicates that corticosteroid treatment may lead to prevention of airway wall remodelling and the development of MMP-12-dependent emphysema in COPD although evidence for this in the airways of asthmatic and COPD patients is limited." (PMID 16359550, 2005). "The role of Mmp-12 in the pathogenesis of emphysema was verified in an independent cohort where β6 knockout mice deficient in the expression of Mmp-12 displayed no alveolar enlargement." (PMID 15585067, 2004). "Furthermore, MMP-12 inhibitors reduce emphysema formation and lung inflammation." (PMID 37592330, 2023). "Interestingly, MMP-12 deficient mice exposed to cigarette smoke do not develop emphysema and exhibit reduced macrophage recruitment to the lung." (PMID 36142454, 2022). "Finally, a negative association was found between serum levels of MMP-12 and renin, which were up-regulated in Cluster 1, and lower prevalence of emphysema." (PMID 36480517, 2022). "Furthermore, IL-13 could promote alveolar macrophage elastase (MMP-12) upregulation, thus leading to emphysema." (PMID 34621758, 2021). "In addition, we show that Vangl2Lp/+ lungs exhibit many of the hallmarks of tissue damage, including an altered macrophage population, abnormal elastin deposition and elevated levels of the elastin-modifying enzyme, Mmp12, all of which are observed in emphysema." (PMID 28237967, 2017). "MMP-12 did not exhibit any significant associations with emphysema sub-types." (PMID 27460105, 2016). "Previously, we reported that sputum MMP-12 concentrations and activity in patients with COPD are directly associated with the extent of emphysema measured by CT suggesting that blocking both MMP-9 and MMP-12 may be more effective than inhibiting either MMP-9 or MMP-12 alone." (PMID 27234393, 2013). "Matrix metalloproteinase (MMP)-12 may be a key mediator in smoke induced emphysema." (PMID 18001475, 2007). "Research has indicated that inhibiting MMP12 activity holds potential for slowing COPD progression, particularly in reducing emphysema and airway remodeling." (PMID 40421300, 2025). "Basophil-derived IL-4 enhances the macrophage production of matrix metalloproteinase-12 (MMP-12), accelerating emphysema progression." (PMID 40244222, 2025). "Targeting the activity of transient receptor potential mucolipin 3 (TRPML3) affects endolysosomal trafficking and phagocytosis of MMP-12 in pulmonary macrophages 39, ultimately reducing COPD-related emphysema incidence." (PMID 39781522, 2025). "Additionally, MMP12 may be a potential therapeutic target for COPD since animal studies have demonstrated that blocking MMP12 can significantly ameliorate the morphological alterations and functional deficits linked to emphysema and small airway remodeling." (PMID 40421300, 2025).
emphysema (continued). "The role of MMP-12 in the development of emphysema is well established, which is in line with our observations of higher MMP-12 concentrations in the participants with emphysema confirmed by pulmonary CT." (PMID 38702427, 2024). "The mechanism of the emphysema is complex, and matrix metalloproteinases, particularly MMP-9 and MMP-12, are of interest; activation of the IL-17 → MCP-1(Ccl-2) → MMP-9 → MMP-12 axis appears to be critical for the formation of emphysema." (PMID 38892239, 2024). "For example, in mouse models, MMP-12 activates CXCL-5 to induce neutrophil infiltration, contributing to emphysema, but in humans, MMP12 performs the function of inhibiting the CXCL family." (PMID 37371940, 2023). "MMP-12 levels and activity from COPD patients’ sputum samples were directly related to the extent of emphysema measured from lung function." (PMID 36830984, 2023). "Another study using IL-13 overexpression in transgenic (TG) mice described the induction of MMP-2, MMP-9, MMP-12, MMP-13, and MMP-14; cathepsins such as B, S, L, H, and K, involved in emphysema development and increased lung inflammation." (PMID 35740358, 2022). "Excess macrophage elastase MMP-12, which is predominantly secreted from alveolar macrophages, is known to mediate the development of lung injury and emphysema." (PMID 35031603, 2022). "As consequence of the backlog MMP-12 accumulates in the extracellular matrix (ECM), with the potential to promote emphysema development." (PMID 35031603, 2022). "Similar conclusions were reported previously indicating that the mechanisms of emphysema include activation of macrophages by LPS release and elastolytic enzymes (proteinase), mainly MMP-2, MMP-9, MMP-12, and cytokines from chemotactic neutrophils." (PMID 34136063, 2021). "This study showed that Mmp12 in adults is upregulated by in utero SHS exposures and is a crucial factor contributing to aggravated lung responses in adult emphysema, asthma, and lung cancer mouse models." (PMID 34912233, 2021). "However, our recent study applied Mmp12-/- mice to demonstrate the pivotal role of this metalloproteinase in driving the autoimmunity in the CS+Eln model, indicating that aside from emphysema, MMP12 may also contribute to the development of airway inflammation." (PMID 33828547, 2021). "The detrimental role of MMP-12 in the pathogenesis of COPD, emphysema, and asthma is also well established." (PMID 32693803, 2020). "Compared with healthy controls, the concentration of MMP-12 in alveolar lavage fluid was significantly higher in COPD patients, which were closely related to the CT markers of small airway diseases and emphysema severity." (PMID 31143784, 2019). "In the early onset of emphysema/COPD mice had increased influx of inflammatory cells and upregulation of MMPs, such as MMP-2, MMP-9, and MMP-12 in the lung." (PMID 30402133, 2018). "Previous studies have shown that IL-17, an important mediator of CS-induced emphysema, induces the expression of inflammatory cytokines and matrix degrading proteinases MMP-9 and MMP-12." (PMID 27363862, 2016). "Despite increased inflammation, extent of emphysema by poly (I:C) was very mild; but was robust and similar for both IAV and RSV infections with enhanced MMP-12 mRNA expression and TUNEL positivity." (PMID 27363862, 2016). "After the development of emphysema, both groups that received the PPE instillation showed an increase in the number of MAC-2-positive (*p = 0.01) and MMP-12-positive (*p = 0.003) cells." (PMID 24886716, 2014). "Matrix metalloproteinase-12 (MMP-12) participates in many pathological processes such as abdominal aortic aneurysm, atherosclerosis, emphysema and cancer." (PMID 23642232, 2013). "Transgenic mice over-expressing MMP-1 develop emphysema, whilst MMP-12 knockout mice are protected from emphysema despite prolonged cigarette smoke exposure, implicating MMP-12 as a compelling emphysema determinant in this model." (PMID 20078883, 2010).
emphysema (continued). "Quercetin prevents progression of emphysema in elastase/LPS-treated mice by reducing oxidative stress, lung inflammation and expression of MMP9 and MMP12." (PMID 20920189, 2010). "Destruction of lung parenchyma in emphysema is thought to occur through excessive proteolysis mediated by the elastin-degrading enzymes MMP2, MMP9, and MMP12 from the MMP family, and by neutrophil elastase from the serine proteinase family." (PMID 15526056, 2004). "Although MMP12 expression increased in the lungs, no emphysema or abnormal collagen deposition was observed, nor was carbon dioxide retention detected in the blood." (PMID 41385483, 2025). "Mechanistically, MMP-12 enhances placental growth factor (PGF) expression and upregulates its downstream signaling molecules, resulting in bronchial epithelial cell apoptosis and emphysema development." (PMID 39781522, 2025). "MMP-12 is known to be involved in the process of elastin degradation leading to emphysema, although exact mechanisms are not known." (PMID 38702427, 2024). "Among these markers, Mmp12 and osteopontin (Spp1) are essential for the development of smoke-induced emphysema in mice whereas MMP-12/SPP-1 levels in sputum were shown to correlate with the extent of emphysema in COPD patients." (PMID 38348034, 2024). "Further, four rock drillers with emphysema confirmed by pulmonary CT, had significantly higher MMP-12 concentrations than 34 rock drillers without emphysema." (PMID 38702427, 2024). "Additionally, the AIM−/− mice showed decreased MMP-12 upregulation at both protein and mRNA levels in the PPE-induced emphysema model." (PMID 37592330, 2023). "Given that Mmp12 ko mice do not develop emphysema we consider the marked repression of Mmp12 as an age-related adaptive response to a lifetime exposure of pathogens and pollutants." (PMID 37932771, 2023). "Increased MMP-12 levels are related to COPD, and a study by Makino shows that continuous MMP-12 production (in response to cigarette smoke, for example) is necessitated to develop emphysema, while neutrophil infiltration exacerbates airway inflammation." (PMID 36293561, 2022). "We further deliver a molecular rationale for the observed lung phenotype in Trpml3−/− mice, we introduce TRPML3 as a regulator of MMP-12 levels in BALF, we provide a possible mechanism for cell entry of MMP-12, and we propose TRPML3 as a potential drug target for COPD and emphysema treatment." (PMID 35031603, 2022). "Overall, Mmp12 in the lungs plays critical roles in acute pro-inflammatory allergen responses, in chronic airway remodeling, and in ECM degradation, highlighting its involvements in emphysema, asthma, and lung cancer pathogenesis." (PMID 34912233, 2021). "Compared to air-elastase controls, in the elastase-induced emphysema model, we demonstrated that 15-week-old female mouse offspring exposed in utero to SHS had significantly enlarged airspaces plus upregulated expression of Mmp12 (10.3-fold)." (PMID 34912233, 2021). "In contrast to CatS, NE was found to contribute to airway neutrophilia and structural lung damage but not mucus obstruction, whereas MMP-12 was identified as a key player in emphysema formation but not leukocyte recruitment or airway mucus obstruction." (PMID 33828414, 2021). "Similar to emphysema, locally enlarged alveolar airspaces did not recover following smoking cessation and, although the infiltration of AMs and expression of MMP-12 improved, they remained higher compared with the normal control group." (PMID 25672547, 2015). "Furthermore, MMP-12 knockout mice were protected from CS-induced emphysema, demonstrating an important role for MMP-12 in the development of emphysema." (PMID 26376849, 2015). "Previous studies have demonstrated that MMP-12 is important in the establishment of a cigarette smoke-induced murine model of emphysema, and that MMP-12 gene knockout can result in the avoidance of emphysema." (PMID 25672547, 2015).
emphysema (continued). "In emphysema, the expression of MMP-9 and MMP-12 is increased." (PMID 26122092, 2015). "The role of MMP-12 is well documented in lung diseases such as COPD, emphysema, and asthma." (PMID 25955565, 2015). "The lung tissues of the patients with advanced emphysema abound in MMP12 protein and mice lacking MMP12 activity are protected against cigarette smoke induced emphysema." (PMID 24587150, 2014). "It has been shown that transgenic mice over-expressing MMP1 or MMP9 develop pulmonary changes comparable to human emphysema, and that mice lacking the MMP12 gene are protected from emphysema despite a long term exposure to cigarette smoke." (PMID 23734748, 2013). "In addition to MMP9, several animal and genetic studies have connected MMP1 and MMP12 to COPD and emphysema." (PMID 23734748, 2013). "The fact that STAT3 negatively regulated MMP-12 is significant as this protease is upregulated in COPD patients and plays a critical role in smoke-induced emphysema in mice." (PMID 24101903, 2013). "MMP12 was previously suggested to play a central role in COPD due to its elastase activity and the fact that MMP12 null mutant mice were entirely protected from cigarette smoke-induced emphysema." (PMID 23090857, 2012). "TiO2 NPs per se did not modify the parameters investigated, but CB NPs increased perivascular/peribronchial infiltration, and macrophage MMP-12 expression, without inducing emphysema." (PMID 22849372, 2012). "Taken together, these data suggest that IL-17RA expression may be affecting two independent processes that are required for the development of emphysema, namely macrophage recruitment via CCL2 and induction of MMP12 by CXCL10." (PMID 21647421, 2011). "By contrast, MMP12 expression decreased with age, suggesting that MMP12, a known contributor to cigarette smoke induced emphysema in murine models, is not the source of elastin turnover with murine aging." (PMID 21713037, 2011). "MMP-12 seems to play an important role in the development of emphysema at least in the mouse model since absence of this specific MMP inhibits the generation of cigarette-smoke induced emphysema in MMP-12 knock out mice." (PMID 16398938, 2006). "The expression levels of MMP-12 were found to be enhanced in BAL, in peripheral blood mononuclear cells (PBMCs) and in serum from patients with COPD compared to healthy subjects, while there is plenty of data supporting that MMP-12 is required for the development of emphysema in mice." (PMID 36835197, 2023). "In animal models, emphysema is not induced by smoking stimulation in MMP-12 knockout mice." (PMID 34425800, 2021). "Attenuating inflammation in the short-term emphysema-exacerbation COPD mouse model; Reducing lung edema and permeability; Decreasing leukocyte infiltration, inflammatory cytokine expression, mucin production, and protease (MMP9 and MMP12) expression in the lung." (PMID 33553219, 2020). "In addition, it has been shown that emphysema induced by chronic CS exposure does not occur in MMP-12−/− mice, indicating that MMP-12 can have a destructive role in COPD." (PMID 30174706, 2018). "Mice lacking MMP-12 are completely protected against emphysema." (PMID 26811900, 2016). "In addition, mice lacking MMP-12 were completely protected from the development of emphysema induced by cigarette smoke." (PMID 27455234, 2016). "For instance, MMP12-knockout mice exposed to cigarette smoke do not develop emphysema." (PMID 27891067, 2016). "Moreover, CS-exposed IL-17RA−/− mice failed to induce CCL2 (MCP1) and MMP12 and did not develop emphysema after 6 months of exposure." (PMID 26284585, 2016). "Therefore, we hypothesized that exposure to TiO2 NPs could lead to and/or aggravate pre-existing pulmonary emphysema, given the roles of MMP-1 and MMP-12 in the pathophysiology of the disease." (PMID 22849372, 2012).
emphysema (continued). "Interestingly, the intratracheal administration of CCL2 can augment emphysema but not in MMP12−/− mice, suggesting that MMP12 rather than macrophages per se is critical for emphysema." (PMID 21647421, 2011). "More recent investigations provide evidence that both, elastase activities, such as MMP-12, and collagenolytic activities, as exerted by MMP-2 and MMP-9, in combination lead to an effective destruction of lung parenchymal tissue that finally results in the generation of emphysema." (PMID 16398938, 2006). "Furthermore, immunohistochemical studies revealed that lung macrophages of participants with emphysema, but not control participants, specifically express MMP12." (PMID 15526056, 2004). "Here, MMP-12 (also termed macrophage metalloelastase MME) has been identified to be of foremost importance in lung destruction, since MMP-12 knockout mice are resistant to smoke induced emphysema, while emphysema can occur independent of MMP-9." (PMID 23720629, 2013). "CS-induced pulmonary inflammation, peribronchial lymphoid aggregates, increase in MMP-12/TIMP-1 mRNA ratio, emphysema and failure to gain weight were not significantly different in Ptx3 KO mice compared to WT mice." (PMID 20920344, 2010). "It is possible that, in our study, these positive effects after the rBmTI-A treatment to minimize and prevent emphysema in a PPE-induced model could be due to an inhibition in neutrophil elastase and a consequent lack of MMP-12 activation." (PMID 24886716, 2014).